GPX4 (glutathione peroxidase 4)
Diseases named in the same sentence as GPX4 in open-access papers (continued):
Sharing a sentence is not in itself a finding about the gene and the disease.
tumor (continued). "Consequently, a more effective antitumor therapy approach involves exploring drugs or mechanisms that deplete GSH, thereby inactivating GPX4 and inducing ferroptosis through the mediation of redox homeostasis in tumor cells." (PMID 38570829, 2024). "We further explored the role of YAP1 in CRPC and showed that YAP1 may be a more suitable target than GPX4 to increase ferroptosis, inhibit tumor recurrence and metastasis, and improve drug sensitivity." (PMID 37773303, 2024). "Ferroptosis is reported to be a tumor suppressor, and targeting GPX4 might be a promising target for therapy." (PMID 38704809, 2024). "Meanwhile, many studies suggest that Erastin (SLC7A11 inhibitor) or RSL3 (GPX4 inhibitor) could inhibit tumor progression and also increasing the chemotherapeutic effect of some chemotherapeutics." (PMID 38600610, 2024). "The application of the DHODH inhibitor brequinar inhibited the growth of tumor cells with low GPX4 expression in vitro, and the combined treatment of brequinar and the SLC7A11 inhibitor sulfasalazine abolished the growth of tumor cells with high GPX4 expression." (PMID 38562175, 2024). "Gss and Gsr expression levels are downregulated together with Gpx4 in the tumor areas which shows that GO-PEI-PEG/PD-L1 siRNAs and sorafenib together could immensely produce anti-tumor immunity actions which improve ferroptosis in vivo." (PMID 38698113, 2024). "Therefore, intervention NRF2/GPX4 pathway was believed can disrupt tumor cell redox homeostasis to prevent cancer progression." (PMID 38396022, 2024). "GPX4 can influence metastasis through several mechanisms including the reduction of oxidative stress, inhibition of ferroptosis regulation of signaling pathways, and interactions within the tumor microenvironment." (PMID 39188677, 2024). "Furthermore, studies have showed that the PI3K-AKT pathway mediates GPX4 function and regulates ferroptosis in tumour cells." (PMID 39881871, 2024). "Notably, tumor cells heavily depend on enzymes such as GPX4 to mitigate oxidative stress and ensure their survival against therapeutic interventions." (PMID 38561331, 2024). "The as-prepared FessMOF nanoparticles exhibit peroxidase-like activity and pH/glutathione-dependent degradability, which enables tumor-responsive catalytic therapy and glutathione depletion by the thiol/disulfide exchange to suppress glutathione peroxidase 4, respectively." (PMID 38715049, 2024). "Furthermore, inhibition of GPX4 not only leads to tumour ferroptosis but also enhances anti-tumour immune function." (PMID 38528461, 2024). "RSL3 acts by inhibiting the enzymatic activity of GPX4 and irreversibly inactivates GPX4, in which Altretamine and Withaferin A as anti-tumor drugs can directly inhibit GPX4-mediated ferroptosis in tumor cells and provide new strategies for anti-tumor therapy." (PMID 38562175, 2024). "Increasing studies suggest that GPX4 is a novel tumor suppressor in many types of cancers." (PMID 39457440, 2024). "Moreover, sorafenib also significantly reduced GPX4 signals in tumor tissues compared to vehicle-treated groups." (PMID 38745179, 2024). "Emerging evidence indicates that the activation of ferroptosis by glutathione peroxidase 4 (GPX4) inhibitors may be a prominent therapeutic strategy for tumor suppression." (PMID 38212623, 2024). "The inhibition of GPX4 not only induces tumor ferroptosis, but also enhances anti-tumor immunity." (PMID 38654314, 2024). "The protein expression of GPX4 was lower in miR-145-5p-overexpressed tumor tissues." (PMID 38247539, 2024). "However, the exact mechanism(s) of how altered GPx4 expression and the emergence of a pro-ferroptotic phenotype can alter tumor aggressiveness and modulate GBM recurrence are uncertain." (PMID 39709480, 2024). "Importantly, the reduced expression levels of NRF2 and GPX4 in xenograft tumor tissues of the CT26PRDX1-KD group were significantly restored by the treatment with TBHQ or Fer-1 as determined by Western blot and IHC assays." (PMID 39430237, 2024).
tumor (continued). "Based on these studies, we speculated that TRIM7 may activate ferroptosis by regulating the SLC7A11/GPX4 axis, thereby inhibiting tumor progression." (PMID 38509147, 2024). "RSL3, a ferroptosis inducer, could directly inactivate GPX4 and promote ferroptosis‐induced cell death in tumor cells." (PMID 39308160, 2024). "Glutathione peroxidase 4 (GPX4) expression in tumor cells and inhibition of the macrophage migration inhibitory factor (MIF) signaling pathway in the TME may be crucial tactics for synergistic cold tumor immunotherapy for GC." (PMID 38928662, 2024). "Taking advantage of in vivo self-assembly, we develop a peptide-ferriporphyrin conjugate with tumor microenvironment specific activation to improve tumor penetration, endocytosis and GPX4 inhibition, ultimately enhancing its anticancer activity via ferroptosis." (PMID 38212623, 2024). "However, the wide application of GPX4 inhibitors in tumor therapy is hampered due to poor tumor delivery efficacy and the nonspecific activation of ferroptosis." (PMID 38212623, 2024). "However, genetic modification of the Nrf-2/GPX4/xCT pathway significantly altered the regulatory effects of SA on tumor cells." (PMID 39430236, 2024). "The expression of FSP1 is positively associated with the resistance of cells to GPX4 inhibitors and is essential for maintaining tumour cell growth in the absence of GPX454." (PMID 38993573, 2024). "To explore whether tumor suppression is caused by ferroptosis, we used ferroptosis markers lipid‐ROS and GPX4 for conducting immunofluorescence staining and histochemical staining in tumor tissues from in vivo experiments." (PMID 39308160, 2024). "An expression cloning approach can identify human tumor cell genes that replace GPX4." (PMID 39055871, 2024). "Additionally, we analyzed the relationship between overall survival and GPX4 expression in tumor tissues from 178 GC patients." (PMID 38369484, 2024). "However, overexpression of GPX4 induces tumor cells to resist ferroptosis, thus diminishing its anti-tumor effects." (PMID 38853203, 2024). "GPX4 activity is regulated by selenium, and targeting GPX4 through covalent inhibitors, proteolysis-targeting chimeras, or cell-type-specific degraders can induce ferroptosis to suppress tumor growth." (PMID 39534872, 2024). "Targeting GPX4 or SLC7A11 has been shown to reduce tumor growth in different NSCLC model systems." (PMID 39400975, 2024). "Interestingly, results indicate that SAS treatment increased transferrin and STEAP-3 expression, while decreased ferritin, SLC7A11, and GPx-4 expression, which are the major drivers that protect the tumor cells from ferroptosis." (PMID 39513121, 2024). "Previous studies have observed decreased methylation in the GPX4 promoter region and increased levels of H3K4me3 and H3K27ac upstream of GPX4 in various tumor cells, indicating a potential link between heightened GPX4 expression, decreased methylation, and increased histone acetylation in tumors." (PMID 38745179, 2024). "MPDA@Fe3O4‐Era plus laser irradiation indicates a highly effective tumor suppression, which raises •OH level, inactivates GPX4, improves small molecule Era bioavailability for potent system xc− inhibition and promotes the development of precise synergistic tumor therapy." (PMID 37984863, 2024). "Additionally, PER1 expression negatively correlates to GPX4 expression, suggesting that under hypoxic conditions, reduced PER1 levels in tumor tissues activate GPX4, leading to resistance against ferroptosis." (PMID 38612455, 2024). "T-cell-derived IFN-γ hinders xCT system function as well as GSH and GPX4 expression in tumor cells." (PMID 38853203, 2024). "We further observed a decrease in GPX4 levels in tumor samples with MCM4 knockdown." (PMID 39290263, 2024).
tumor (continued). "In addition, epigenetic modifications regulate ferroptosis in tumor cells by modulating key ferroptosis-related proteins, such as GPX4, ACSL4, SCL7A11, FTH1, FSP1." (PMID 38654314, 2024). "However, the wide application of GPX4 inhibitor in tumor therapy is hindered due to the poor tumor delivery efficacy and nonspecific activation of ferroptosis." (PMID 38212623, 2024). "Therefore, it is encouraging to develop nanosystems, which can suppress GPX4 expression in cancer cells, facilitate or trigger the Fenton reaction and regulate exogenous lipid peroxidation inside tumor cells." (PMID 38698113, 2024). "Furthermore, this discovery demonstrates that inhibiting GPX4 not only induces tumour ferroptosis but also enhances anti‐tumour immunity." (PMID 38140764, 2024). "Moreover, key ferroptosis factors GPX4 and ACSL4 are closely associated with multiple tumor-related signaling pathways, including tumor proliferation, EMT, angiogenesis, and tumor inflammation pathways." (PMID 39335103, 2024). "The small molecule N6F11 serves as an inducer of ferroptosis, causing degradation of glutathione peroxidase 4 (GPX4) in tumor cells without affecting GPX4 levels in immune cells." (PMID 39223632, 2024). "Overexpression of GPX4 can protect tumor cells from the effects of ferroptosis." (PMID 39273090, 2024). "However, in the tumor specimens collected at our hospital, immunohistochemistry revealed that GPX4 expression was higher in postchemotherapy patients (n = 6) than in prechemotherapy patients (n = 6) with OS." (PMID 39721999, 2024). "Likewise, LASS2 overexpression reversed the changes in the levels of FTH1, FTL and GPX4 induced by either Fer-1 or erastin in these tumour cell lines." (PMID 38419028, 2024). "GPX4 (glutathione peroxidase 4) is a lipid hydroperoxidase that is critical to tumor survival." (PMID 38399303, 2024). "Additionally, Treg-specific ablation of GPX4 inhibits tumor growth and enhances the body’s ability to fight against tumors." (PMID 38962561, 2024). "GPX4 has been proved to affect tumor EMT by regulating ROS molecules." (PMID 38333875, 2024). "The exact role of GPX4 in HCC formation remains unclear; however, it has been demonstrated that GPX4 acts as a tumor suppressor in HCC, particularly when there is significant proliferation." (PMID 38650929, 2024). "Cell type-specific degraders: While covalent inhibitors and PROTAC degraders hold promise for inhibiting tumor growth, they may affect both cancerous and normal cells due to the widespread expression of GPX4." (PMID 38844964, 2024). "It is necessary to explore whether NEDD4L could suppress tumor progression via targeting other ferroptosis core genes, such as GPX4, ASCL4 and FTH1." (PMID 39557844, 2024). "In conclusion, these studies have emphasized the CD8+ T cell promoting tumor cell ferroptosis, suggesting that targeting the Xc-/GSH/GPX4 pathway in combination with anti-PD-1/PD-L1 antibody may be an effective tumor immunotherapy combination strategy." (PMID 39359721, 2024). "The peroxide bridge structure of DHA triggers a Fenton reaction with the release of iron ions that may contribute to ferroptosis in tumor cells by promoting transferrin receptor expression and inhibits glutathione peroxidase (GPX4)." (PMID 38738174, 2024). "However, when combined with sulfasalazine, which has iron-inducing activity, this inhibitor can synergistically induce ferroptosis and inhibit high-GPX4 tumor development." (PMID 38313306, 2024). "Thus, GPX4 inhibitors are able to increase the therapeutic efficacy of platinum-based drugs against drug-resistant tumor cells." (PMID 38469234, 2024). "Furthermore, IHC staining and immunoblotting analysis of BALB/c mouse-derived tumor tissues suggested that BCHE reduced GPX4 expression and increased transferrin expression in vivo." (PMID 38906931, 2024).
tumor (continued). "Moreover, the relationships among BUB1b, NRF2, and GPX4 were further investigated via IHC staining in a TMA containing 92 LUAD tumor tissues and matched paratumor tissues." (PMID 39043653, 2024). "Insufficient GPX4-mediated lipid peroxide detoxification leads to lipid peroxide accumulation, resulting in degradation of the plasma and organelle membranes, which can drive tumor cell death." (PMID 39595619, 2024). "However, inhibition of iPLA2β activity in tumor cells has been reported to induce GPX4-independent ferroptosis and iPLA2 activity of PRDX6 was a negative regulator of ferroptosis." (PMID 39601357, 2024). "In this context, the intracellular accumulation both of reduced GSH and GPX4 might promote cell survival and growth as these contributed to reduce toxicity of excess ROS in tumor cells." (PMID 39666242, 2024). "Notably, the high expression levels of SLC7A11 and GPX4 were related to tumour diameter, distant metastasis, and clinical stage of RCC (P<0.05) but not to age, sex, lymph node metastasis, or pathological differentiation (P>0.05)." (PMID 37807410, 2023). "Gpx4−/−-Gpx4-K90R MC38 tumor bearing mice exhibited a significant delay in tumor growth as shown in volume and weight compared with Gpx4−/−-Gpx4-WT tumors, while Gpx4−/−-Gpx4-K90R/D23N MC38 tumor bearing mice showed similar tumor development with Gpx4−/−-Gpx4-WT tumors." (PMID 37502961, 2023). "In addition, GPx4 can also promote tumour proliferation, invasion and metastasis by maintaining stemness." (PMID 36923926, 2023). "Next, we explored whether GPX4 knockdown plays a tumor suppressor role by regulating the immune microenvironment." (PMID 37649598, 2023). "Thus, it was concluded that GPX4 is a key regulator of tumor progression and vessel maturation through 12/15-LOX activity control." (PMID 36675129, 2023). "Moreover, inhibition of GPX4 by RSL3 has been reported to markedly enhance the anticancer effects of cisplatin by inhibiting tumor growth." (PMID 37488128, 2023). "Additionally, the ethanol extract of Camellia nitidissima Chi (CNC) and Lycium barbarum polysaccharide (LBP) can also inhibit several tumor cells by decreasing the level of expression of GPX4 and SLC7A11 proteins to boost ROS accumulation." (PMID 37833746, 2023). "However, targeted inhibition of SLC7A11 or GPX4 has been shown to sensitize tumor cells to radiotherapy, leading to increased effectiveness." (PMID 37980334, 2023). "However, some tumour cells can still resist ferroptosis after inhibition of GPX4, which indicates the existence of GPX4-independent defence pathways against ferroptosis." (PMID 37954843, 2023). "Studies have indicated that GPX4 inhibitors strongly enhance the activation of T cells in the tumor microenvironment when combined with immunotherapy, which could provide novel insights into precision medicine for LAR-TNBC." (PMID 38065948, 2023). "Then, we analysed the expression of RBMS1, GPX4, and 4HNE in mice xenograft tumours." (PMID 36989117, 2023). "Despite the prevailing importance of GPX4 and CoQH2 for limiting ferroptosis, both the signal pathways and the tumor microenvironment influence the function of ferroptosis in tumorigenesis and tumor therapy.This section focuses on the role of these two pathways that inhibit ferroptosis." (PMID 38125948, 2023). "It has been recently reported that Gpx4-deficient Treg cells may have a potential role in promoting the activation of Dendritic cells (DC) and the function of CD8+ T cells in suppressing tumor growth." (PMID 36845720, 2023). "In contrast, APS treatment reduced the expression of GPX4 in the tumor tissues of nude mice." (PMID 37733667, 2023). "Moreover, elevated cellular MDA, 4-HNE and ROS levels were observed in TRIM26-knockdown tumor cells, which was reversed by the re-expression of GPX4." (PMID 37872147, 2023).
tumor (continued). "The immunohistochemistry analysis of the tumor tissue showed that the mean area that stained positively for Ki-67, which is associated with proliferation, and SLC7A11 and GPX4, which are associated with anti-ferroptosis, were smaller under GRh3 treatment than in the control samples." (PMID 37092860, 2023). "hypothesized that GPX4 played a putative regulatory role during tumor progression and conducted an experiment to inactivate GPX4 in murine embryonic fibroblasts (MEFs)." (PMID 36675129, 2023). "Most importantly, RPLP2 positively associates with ferroptosis suppressor GPX4, and inhibition of RPLP2 could lead to the acceleration of ferroptosis to suppress tumor progression of HCC." (PMID 37980521, 2023). "Furthermore, clinical data from TCGA and GTEx further confirmed the increase of NeuroD1 and GPX4 in various tumor tissues." (PMID 38134213, 2023). "However, some tumor cells can use glutathione peroxidase 4 (GPX4), a lipid repair enzyme, to decrease LPO accumulation by converting toxic LPO to non-toxic lipid alcohols in the presence of glutathione (GSH), thereby protecting themselves from ferroptosis." (PMID 37563614, 2023). "Overexpression of GPX4 confers resistance to ROS-induced cell death in tumor cells." (PMID 37807410, 2023). "PARL and STARD7 may therefore represent promising targets to induce ferroptosis in tumours resistant to GPX4 inhibitors." (PMID 36658222, 2023). "Genetic inhibition of GPX4 can induce tumor cell ferroptosis and suppress tumor growth in vivo." (PMID 37229486, 2023). "In addition to regulating antioxidant systems such as GPX4 and system Xc−, tumor‐related signaling pathways affect the activity of enzymes required for lipid peroxidation such as ALOX12." (PMID 37229485, 2023). "S-N/NiPSAE could produce •OH and consume GSH more efficiently than N/Ni PSAE in ferroptosis-based tumor therapy, inducing GPx-4 inactivation and irreversible LPO, leading to ferroptosis of tumor cells and better inhibition of tumor growth." (PMID 37958697, 2023). "Furthermore, to evaluate the efficacy of icFSP1 in a tumour-bearing mouse model, Gpx4 and Fsp1 double knockout B16F10 cells overexpressing hFSP1 were subcutaneously injected into female C57BL/6J mice." (PMID 37380771, 2023). "In addition, PB can also suppresses tumor growth in an orthotopic mouse model of GC via regulating the expression of GPx4, TFR1, NOCA4 and FTH1 in vivo." (PMID 36923926, 2023). "Surprisingly, transformed GPX4+/− survived in Matrigel and produced tumor spheroids." (PMID 36675129, 2023). "Moreover, combination treatment of darapladib with the GPX4 inhibitor PACMA31 efficiently inhibits tumour growth in a xenograft model." (PMID 37714840, 2023). "Collectively, our results demonstrated that CH‐OD‐SSZ hydrogel could inhibit SLC7A11/system xc− to induce the depletion of intracellular GSH and simultaneously inhibit GPX4 expression to promote the ferroptosis of tumor cells." (PMID 37132587, 2023). "In addition, IL-1B is expressed during the ferroptosis process of GPX4-deficient Treg, promoting the activation of DCs and CD8+ T cells, and inhibiting tumor growth." (PMID 38288118, 2023). "Moreover, genome-wide expression profiling analysis and subsequent assays revealed that the anti-tumor effects of the combined treatment were at least partially mediated via the induction of ferroptosis through the dual suppression of GPX-4 and FSP-1." (PMID 36986483, 2023). "However, the effect of GPX4 inhibitors on tumor immunity and tumor growth through Tregs in different cancer types needs further investigation." (PMID 36926345, 2023). "This implies that GPX4 knockdown may enhance tumor cell immunogenicity and prevent tumor cells from escaping immune surveillance." (PMID 37649598, 2023). "Moreover, the tumor features resembled GPX4-dysregulated ferroptosis, with a representative marker of ferroptosis." (PMID 37046995, 2023). "The data uncover the value of targeting GPX4 to effectively sensitize tumor cells to CTX." (PMID 36899869, 2023).